SAA2 (serum amyloid A2)
Diseases named in the same sentence as SAA2 in open-access papers (continued):
Sharing a sentence is not in itself a finding about the gene and the disease.
infection (29 papers, 2010 to 2026). The state of being infected such as from the introduction of a foreign agent such as serum, vaccine, antigenic substance or organism. "Compared to viral RNA detection (e.g., RT-PCR), which requires high viral load for sensitivity, SAA2 levels rise early in infection due to its role in the acute-phase response." (PMID 40158620, 2026). "SAA1 and SAA2 are released into blood stimulated by IL-6 in response to infection, inflammation, injury, or stress." (PMID 40283676, 2025). "Overexpression of Saa1, Saa2, Saa3, and Saa4 in macrophages enhances NF-κB-mediated pro-inflammatory cytokine production and bacterial clearance during infection." (PMID 40061939, 2025). "Serum amyloid A proteins, specifically SAA1 and SAA2, significantly upregulated during the infection phase." (PMID 40568583, 2025). "As expected, we found that their levels were similar (SAA1 and SAA2) or increased (CRP) to a greater extent in patients with more severe infection symptoms (NIH-2 group) during infection compared to those with mild to moderate characteristics (NIH-1 group)." (PMID 39183264, 2024). "The serum amyloid A proteins (SAA1 and SAA2), which are acute phase apo-lipoproteins reported to play an important role in inflammation, infection and tissue repair were found to be up-regulated in both time-points studied." (PMID 35585182, 2022). "In a previous proteomic study, we evaluated the expression of the different isoforms (SAA1 and SAA2) as predictors of infection development." (PMID 34200779, 2021). "The major acute phase proteins Alpha-1 antitrypsin (A1AT) members 1 and 3, Haptoglobin, Hemopexin, Alpha-1 acid glycoprotein, CRP, and SAA2 reached comparable maximum fold change values at the common post-infection time-points between the infection types." (PMID 30774579, 2019). "SAA1 can bind retinol and can provide it during an infection – mice deficient in both SAA1 and SAA2 have increased bacterial numbers in spleen and liver following acute infection." (PMID 30165816, 2018). "SAA2 is important in the initial response to infection and its expression is activated by pro-inflammatory cytokines." (PMID 25901897, 2015). "The production of two types of SAA protein—SAA1 and SAA2—is massively increased in the liver during the immediate immune response following an infection or during microbial colonization of the intestinal epithelium." (PMID 25182850, 2014). "Both infections induced increased hepatic expression of SAA2, SAA3, and SAA4 as well as pulmonary and splenic expression of SAA3." (PMID 24146912, 2013). "A substantially increased expression of SAA2 in the liver of infected pigs compared with control pigs was found in both infection experiments." (PMID 24146912, 2013). "Furthermore, there were nine proteins that were specifically detected at 7 days post-infection (Saa2, Trappc1, Cxadr, Armc8, Hbxip; Lamtor5, Prppsap2, Usp46, Pcdh10, Neo1)." (PMID 36061859, 2022). "SAA1 and SAA2 expression levels are increased with infection, inflammation, and injury." (PMID 31188831, 2019). "Further PRM analyses were performed on the same 20 patients in order to evaluate whether either of the acute phase isoforms (SAA1 and SAA2) had a more significant effect on infection and inflammatory processes." (PMID 28701906, 2017). "In the increased proteins, serum amyloid A1 (SAA-1) and serum amyloid A2 (SAA-2) are acute phase lipoproteins rapidly produced in the liver with trauma or infection, and the serum amyloid proteins potently enhance cytokine production from peripheral blood mononuclear cells." (PMID 23763817, 2013). "SAA2 regulation was negligible in spleen tissue in both infection experiments." (PMID 24146912, 2013). "Increased expression of several acute-phase reactants, such as amyloid A proteins (Saa1, Saa2, Saa3), amyloid P component serum (Apcs), haptoglobin (Hp), hemopexin (Hpx) and orosomucoid 2 (Orm2), was observed only in CerS2-null mice after transfer of iNKT cells and infection with LCMV." (PMID 29163475, 2017).
infection (continued). "Proteins like CRP, SERPINA3,SAA1, SAA2, and immunoglobulins were previously related to SARS-CoV-2infection in the literature,−, and their abundance increasesduring the infection and returns to their normal status after 3–4weeks postinfection." (PMID 40997940, 2025). "It is reported that two members of which (SAA1 and SAA2) are (along with CRP) the most prominent members of the acute phase response (APR) during which their serum levels rise dramatically after trauma, infection and other stimulation." (PMID 38243232, 2024). "So antibiotics cause damage to the organism after regulating intestinal microorganisms or after infection, activating two factors, CD74 and SAA2, and activating a large number of genes and cells at the same time." (PMID 37193034, 2023). "When interleukin-6 (IL-6) is stimulated in response to infection, inflammation, injury, or stress, the acute phase SAA proteins SAA1 and SAA2 are released into the blood." (PMID 36264449, 2022). "The proteomics and Luminex data showed that various macrophage and neutrophil related cytokines and chemokines like MCP-1, IP-10 (CXCL10), MIG, MIP-1β (CCL4), CXCL8 (IL-8), SAA2, and AXL were dramatically upregulated at 7 days after infection." (PMID 35903092, 2022). "Of these genes, SAA2 was the most significant (-10logp-value of 81); the distinctive genes in the SARS-CoV-2’s infection response were CSF3, CSF2, IL1B, and PTGS2." (PMID 33301474, 2020). "Among these, family of SAA (particularly the SAA2 and SAA3) was highly induced throughout the infection period." (PMID 21110886, 2010). "The FFGHGAEDSLADQAANEWGR peptide, unique to SAA1, and the tryptic SAA2 GPGGAWAAEVISNAR peptide appeared to be significantly more abundant in patients suffering from an infection than in patients without one." (PMID 28701906, 2017). "The oncogenic transcription factor Stat3 was down-regulated in both the proximal and the middle section, and the same pattern holds in middle and distal sections for Saa2, a member of the family of APR proteins that is usually up-regulated during infection, tissue damage or inflammation disease." (PMID 26861690, 2016). "Acute phase proteins, such as C-reactive protein (CRP), Serum Amyloid A2 (SAA2), and Lipopolysaccharide binding protein (LPS-BP) were increased several fold in both infection types, but were not present at high enough levels to be quantitated in the naive NHP plasma samples." (PMID 30774579, 2019).
tumor (18 papers, 2019 to 2025). "Among them, in particular, serum amyloid A proteins, SAA1 and SAA2, secreted by cancer cells, cancer-associated fibroblasts, tumor-associated macrophages and adipose cells in the tumor microenvironment, may promote cancer cell proliferation, metastasis and survival." (PMID 41387465, 2025). "One example is that acute-phase Saa1 and Saa2 production in mouse liver serves to abrogate tumor surveillance by T cells, thus promoting tumorigenesis." (PMID 39940756, 2025). "SAA2 expression was linked to the presence of burrs on tumour edges, and CXCL9 expression was associated with age of onset and tumour stage." (PMID 41228202, 2025). "Survival analysis, in conjunction with heightened SAA2 expression, outlined reduced disease-specific survival, overall survival, and a progression-free interval, signaling a trend towards advanced tumor staging." (PMID 39457484, 2024). "According to our results and previous studies, it is a reasonable inference that SAA2 is related to tumor tumorigenesis and poor survival of EC patients." (PMID 37430202, 2023). "The bulk RNA-seq data from validation cohort 2 also revealed higher SAA1 and SAA2 expression levels around the border areas (bilateral sampling of 5 mm-wide tissues along the border) than in the corresponding tumor and paratumor tissues (n = 10)." (PMID 37337030, 2023). "The mRNA expressions of the majority of genes, including IL13RA2, IL20 and SAA2, were persistently higher in tumor cells lines than Het-1A cells." (PMID 37430202, 2023). "mRNA expression of SAA2 was similar in healthy and tumor samples, but CFB was significantly more expressed in tumor samples." (PMID 34670568, 2021). "As expected, we observed an increase in the levels of markers that are important for immune responses and inflammation (Saa1, Saa2, Lcn-2, Ltf, and Orosomucoid-2) and initiating and promoting tumor growth (Ighg1, Scube3, and Fgl1)." (PMID 33110211, 2020). "Two missense variants (SAA2 and SLC6A5) were heterozygous in blood and homozygous in the tumor and both are located on chromosome 11 in the LOH region." (PMID 33379206, 2020). "In addition, distinct RCC single-cell RNA-seq datasets illuminated SAA2 visibility across various cancers, predominantly in fibroblasts, endothelial cells, and tumor cells." (PMID 39457484, 2024). "Previous works also highlighted the role of SAA2 in tumor progression." (PMID 39457484, 2024). "To examine MDSC-tumor interactions, we analyzed the GSE145374 dataset, identifying CSF2, SAA2, IL6, SAA1, and BCL2A1 as the top five upregulated differentially expressed genes in SKOV3 cells after co-culture with MDSCs." (PMID 41029721, 2025). "Consistently, supplementing primary HER2-positive tumor cultures with recombinant SAA1, SAA2, or THBS4 peptides enhanced tumor cell proliferation and migration." (PMID 41387465, 2025). "Collectively, these studies suggest that SAA2 is not only a pro-cancer molecule, particularly in RCC, but also facilitates tumor progression through various mechanisms, including inducing immune suppression or evasion." (PMID 39457484, 2024). "Regarding the surrounding normal hepatocytes, a recent paper identified an invasive zone around the iCCA tumor border containing a subpopulation of damaged hepatocytes with increased serum amyloid A1 (SAA1) and A2 (SAA2) expression." (PMID 39256888, 2024). "Within the 250 μm wide region adjacent to the tumour border, the damaged area induces high expression of SAA1 and SAA2 by CXCL6." (PMID 39350478, 2024).
tumor (continued). "Within the zone, intense suppression of the local immune microenvironment, metabolic reprogramming of tumor cells, and severely damaged hepatocytes with high expression of serum amyloid A1 and A2 (SAA1, SAA2, referred to collectively as SAAs) were noted." (PMID 37337030, 2023). "We next measured SAA2 and CFB levels in plasma samples from patients with (M1) or without metastases (M0), collected before or after surgical resection of the primary tumor." (PMID 34670568, 2021). "Based on the intersection of APP signature between human BC tissues and cell lines to exclude the tumor heterogeneity, SAA1 and SAA2 were highly expressed both TNBC tissues and cell lines." (PMID 30728901, 2019). "In addition, although NP mice exhibited significantly shorter tumor-free survival compared to N mice, and SAA1, SAA2, and THBS4 enhanced HER2/neu+ cancer cell proliferation in vitro, Ki67 staining of tumor sections did not reveal differences in proliferation between N and NP tumors." (PMID 41387465, 2025).
cancer (15 papers, 2011 to 2025). A tumor composed of atypical neoplastic, often pleomorphic cells that invade other tissues. "Previous studies indicated that high level of SAA2 was associated with the progression of inflammatory disease, including cancer." (PMID 36159801, 2022). "This work relates hepatic Saa expression and elevated blood Saa levels (mainly Saa1 and Saa2) to the metastasis of cancer cells in the digestive system, which results from an Saa-induced local environmental change." (PMID 39940756, 2025). "With the aim of unveiling the single-cell transcriptomic dynamics of SAA2 within cancer and its implications on cellular divergence, a meticulous examination of pan-cancer single-cell RNA sequencing databases was pursued." (PMID 39457484, 2024). "SAA2 has a unique role in promoting Th17 cell-mediated inflammatory disease and plays an important role in many cancers, including GBM." (PMID 35855914, 2022). "Cancer-associated inflammation was shown to be linked with an increase of serum amyloid A proteins (SAA1 and SAA2 isomers)." (PMID 28250368, 2014). "4T1 cancers elevate the expression of SAA1 and SAA2, the two major murine acute phase proteins in the liver." (PMID 36817472, 2023). "Furthermore, the expression of QPCTL was positively correlated with SAA1, POSTN, PLA2G2A, SAA2,C6orf15, H19, PI3, etc., whose expression also affects cancer progress." (PMID 37063864, 2023).
bacterial infection (2 papers, 2014 to 2025). "In a more recent study, the investigators used Saa TKO mice (triple knockout of the mouse Saa1, Saa2 and Saa3) to demonstrate that these mice were more susceptible than the wild-type controls to bacterial infection as they succumbed to different ways of bacterial infections." (PMID 39940756, 2025). "We find that Saa1/2−/− mice, which harbor deletions of both the Saa1 and Saa2 genes, have higher bacterial burdens in spleen and liver following an acute bacterial infection, supporting an essential role for SAAs in the response to microbial challenge." (PMID 25073702, 2014).
metabolic disease (2 papers, 2020 to 2023). A congenital disorder (due to inherited enzyme abnormality) or acquired (due to failure of a metabolically important organ) disorder resulting from an abnormal metabolic process. "While much prior work has focused on the hepatic acute-phase SAA1 and SAA2 subtypes, important roles for extra-hepatic SAA in the chronic inflammatory processes associated with metabolic diseases are now emerging." (PMID 37396595, 2023).
SAA2 also shares sentences with these, for which no sentence is quoted: rheumatoid arthritis (3 papers); anemia (2); breast tumor (2); cardiovascular disease (2); acne (1); clear cell renal carcinoma (1); colon adenocarcinoma (1); colorectal tumors (1); coronary atherosclerosis (1); coronary heart disease (1); Crohn disease (1); depression (1); esophageal cancer (1); experimental autoimmune encephalomyelitis (1); gastric cancer (1); Lewis lung carcinoma (1); myocardial infarction (1); neurofibromatosis (1); ovarian carcinoma (1); pancreatic cancer (1); polyposis (1); prostate carcinoma (1); psoriasis (1); renal adenocarcinoma (1); renal carcinoma (1); septic shock (1); Shock (1); Splenomegaly (1); systemic lupus erythematosus (1); yang deficiency (1).